ACADM (acyl-CoA dehydrogenase medium chain)
Diseases named in the same sentence as ACADM in open-access papers (continued):
Sharing a sentence is not in itself a finding about the gene and the disease.
cardiac hypertrophy (1 paper, 2021). "Network analysis mapping protein–protein interactions and synergistic actions of AR using multi-component networks reveal drug targets such as ACADM, COX4I1, COX6B1, HBB, MYH14, and SLC25A4, as potential pharmacological co-targets for cardiac hypertrophy." (PMID 33589646, 2021).
colitis (1 paper, 2024). Inflammation of the colon. "Our data showed that the enzymes ACSL1 and ACADM, which break down long-chain fatty acids and medium-chain fatty acids, respectively, were significantly decreased in colitis." (PMID 38668322, 2024).
diabetic cardiomyopathy (1 paper, 2020). Diabetic cardiomyopathy is a disorder of the heart muscle in people with diabetes. "ACADM could be a rate-limiting factor for the initial step of the mitochondrial fatty acid beta-oxidation catalyzation, which plays a vital role in myocardial infarction and diabetic cardiomyopathy." (PMID 32565767, 2020).
familial hypertrophic cardiomyopathy (1 paper, 2020). Hypertrophic cardiomyopathy caused by mutations in the genes encoding components of the sarcomere, in the absence of predisposing conditions. "Human genome-wide association studies (GWAS) have indicated that mutations in HADHA and HADHB are associated with familial hypertrophic cardiomyopathy, and mutations in CPT1, ACADM, and ACAA2 genes are associated with impaired mitochondrial fatty acid β-oxidation." (PMID 32804947, 2020).
Hypercholesterolemia (1 paper, 2020). An increased concentration of cholesterol in the blood. "We also found altered DNA methylation in patients with hypercholesterolemia, in key genes associated with fatty acid transport and metabolism (hypomethylated: PPARD, PPARG, SLC27A1, SLC27A3 and SLC25A20, and hypermethylated: ANGPTL4, ACLS6, ACADM and CPT1A)." (PMID 33028190, 2020).
melanoma (1 paper, 2021). A malignant, usually aggressive tumor composed of atypical, neoplastic melanocytes. "Sebacic acid is a medium chain acyl-coenzyme A dehydrogenase (ACADM), metabolite that is present in a variety of tumors, such as squamous cell carcinoma of the skin and melanoma." (PMID 34795577, 2021).
type 2 diabetes (1 paper, 2024). "ACADM, an acyl-CoA dehydrogenase medium chain gene, is a medium-chain fatty acid oxidant and is upregulated in both type 1 and type 2 diabetes patients, as analyzed from public data." (PMID 38336726, 2024). "Correspondingly, we observed upregulation of ACADM in both type 1 and type 2 diabetes patients by analyzing public databases." (PMID 38336726, 2024).
ulcerative colitis (1 paper, 2023). An inflammatory bowel disease involving the mucosal surface of the large intestine and rectum. "After integrating the multi-omics data between mQTL-eQTL and eQTL-pQTL, we identified two mitochondrial genes, i.e., PARK7 and ACADM, with tier 1 evidence for their associations with IBD and ulcerative colitis (UC)." (PMID 38103512, 2023).
tumor (21 papers, 2017 to 2025). "Immunohistochemical experiments showed that ACADM levels were significantly higher in patients with tumor recurrence." (PMID 37612627, 2023). "The level of ACADM expression decreases with increasing tumor stage and grade." (PMID 38361759, 2024). "For example, ACADM was significantly expressed at low levels in HCC, and suppression of ACADM could increase the levels of triglycerides, phospholipids, and LDs, indicating that it has a tumor inhibitory effect on HCC." (PMID 39002673, 2024). "In our study, the FOXP3 expression and Tregs were high in low-ACADM group, implying that ACADM might influence the Tregs infiltration in the tumor microenvironment and the prognosis of ccRCC patients." (PMID 38664460, 2024). "In this study, we observed decreased levels of ACADM-mRNA and protein in most types of tumors, which revealed that ACADM might serve as a tumor suppressor gene, which was probably involved in tumor development." (PMID 38664460, 2024). "This indicates to some extent that ACADM may be able to alter the growth of the tumor by having an effect on the immunological milieu inside the tumor itself." (PMID 38361759, 2024). "Three hub genes (EHHADH, ACADM and AGXT2) were met the criterion of both WGCNA and PPI networks analysis, which showed highest negative association with pathological T stage (r = - 0.45, p = 0.01) and tumor grade (r = - 0.45, p = 0.01)." (PMID 31839812, 2019). "In comparison to the normal group, the expression levels of ACADM and ALDH1A1 were significantly down‐regulated in the tumor group, whereas the expression level of DHCR7 was significantly up‐regulated in the tumor group." (PMID 39716927, 2025). "Stimulated lipolysis in malignant CAAT supported upregulated peroxisomal and mitochondrial β-oxidation in both CAAT and tumor tissue since they generally displayed increased protein level of ACOX1 and ACADM." (PMID 38247846, 2024). "Previous studies show that ACADM and ACAT1 are protective tumor suppressors of KIRC, which is consistent with our findings." (PMID 36059510, 2022). "We detected seven pairs of ccRCC tissues and corresponding para-carcinoma tissues and found a significantly lower level of ACADM and ACAT1 mRNA and a higher level of CPT1B and HACD1 mRNA in tumor tissues." (PMID 35873479, 2022). "Furthermore, we examined the expression levels of ACADM, FASN, ACC1, ELOVL5, and FABP1 in primary tumor tissues and TD tissues through IHC methods." (PMID 39495391, 2024). "The anti-tumor actions of ACOX1, ACAT1, ACADVL, and ACADM were identified as prospective targets." (PMID 37538114, 2023). "Moreover, a significant negative correlation was observed between exo-ACADM and tumor weight (r=-0.41) after gemcitabine treatment." (PMID 37612627, 2023). "To do this, we investigated the expression of IDO1 and medium-chain Acyl-CoA Dehydrogenase (ACADM) in primary and metastatic PCa by analyzing gene expression profiles from datasets containing androgen-ablation resistant PCa metastatic samples and normal and tumor adjacent tissues." (PMID 31842810, 2019). "Therefore, EHHADH, ACADM and AGXT2 could be suggested as protective tumor suppressors for ccRCC." (PMID 31839812, 2019). "Our findings suggest that the hypermethylated ACADM found in the PPAT of OB/OW PCa patients might fail to generate medium-chain acyl-CoA β-oxidation and result in MCFA and LCFA accumulation in adipose tissue, providing a favorable tumor microenvironment for PCa cell aggressiveness." (PMID 29692867, 2018).
cancer (17 papers, 2017 to 2024). A tumor composed of atypical neoplastic, often pleomorphic cells that invade other tissues. "For investigating ACADM-related mechanism underlying cancer occurrence, ACADM-binding proteins and their correlated genes were screened for functional analysis." (PMID 38664460, 2024). "ACADM has been linked to metabolic diseases, cancer, and pathogen infections and changes in its expression were also observed in theses process." (PMID 39002673, 2024). "We employed the “Gene_DE” module of the TIMER2.0 web tool for exploring ACADM-mRNA expression pattern in pan-cancer." (PMID 38664460, 2024). "Firstly, authors analyzed the possible link between ACADM and cancer immune infiltration by bioinformatics methods, but unfortunately, there are not enough biological experiments to support the findings." (PMID 38361759, 2024). "ACADM has been extensively involved in the pathogenesis of diseases, especially in cancer, owing to its importance in the β-oxidation of MCFA." (PMID 39682455, 2024). "Among the 102 feature genes, eight genes (MYLK, GADD45A, ACADM, UQCR11, TST, PTCD3, SOD1, CD151) were significantly enriched in the cancer hallmark of adipogenesis." (PMID 36905391, 2023). "Several studies have revealed the important value of ACADM in the prognosis of different cancers." (PMID 38664460, 2024). "However, medium-chain acyl-CoA dehydrogenase (ACADM) encodes an important enzyme responsible for fatty acid β-oxidation (FAO) and its association with prognosis and immunity in cancers has rarely been reported." (PMID 38664460, 2024). "In addition, this research also revealed the biological role of ACADM and its impact on cancer infiltration by immune cells." (PMID 38361759, 2024). "Finally, we used cancer cell lines and clinical tissues to confirm the bioinformatics results of ACADM." (PMID 38664460, 2024). "A similar pattern was seen in the protein level of lipolytic enzyme ATGL and β-oxidation enzymes, ACOX1 and ACADM, whose protein levels were higher in malignant tumor tissue of obese women compared to malignant tumor tissue of normal-weight women but also compared to their benign counterparts." (PMID 38247846, 2024). "Besides, relation of ACADM-mRNA with prognosis pan-cancer was analyzed, which suggested that ACADM down-regulation predicted dismal OS in ESCA (P = 0.039) and KIRC (P < 0.001)." (PMID 38664460, 2024). "Another study also reported that attenuating ACADM activity accelerated cancer progression." (PMID 33856140, 2021). "Although the molecular pathological mechanisms of low expression of ACADM in cancer remain unclear, study has shown that HIF-1 mediated suppression of acyl-CoA dehydrogenases and fatty acid oxidation is critical for cancer progression." (PMID 31788359, 2019). "Both the log-rank test and the univariate Cox regression analysis confirmed that lower expression of CPT2, ACAA2 and ACADM in cancer tissues could predict poor prognosis of CRC patients." (PMID 28977850, 2017). "However, the effects of ACADM on cancer have been scarcely studied." (PMID 37612627, 2023). "Wilcoxon rank sum test was used to assess the levels of acyl-CoA dehydrogenase medium chain (ACADM) between KIRC and non-cancer samples." (PMID 38361759, 2024). "It is known that the roles of ACADSB, ACADM, HADH, PYCR1 and ITPKA have been explored in cancers, whereas PAFAH2 not12–16." (PMID 37460577, 2023). "In the present study, FASN was shown to be upregulated in ACTH-PAs, which was similar to other types of cancer, while enzymes related to fatty acid catabolic metabolism, such as ACADVL, ACADM, and ACAA2, were downregulated in ACTH-PAs." (PMID 30532734, 2018).
metabolic disorder (10 papers, 2023 to 2026). "Medium-Chain Acyl-CoA Dehydrogenase Deficiency (MCADD) is a metabolic disorder caused by mutations in the ACADM gene, leading to impaired fatty acid oxidation." (PMID 41002789, 2025). "Medium-chain acyl-CoA dehydrogenase deficiency results from ACADM mutations, which represents a frequently seen hereditary metabolic diseases among the Caucasian population." (PMID 38664460, 2024). "Medium-chain acyl-CoA dehydrogenase (ACADM) is an enzyme participating in lipid metabolism associated with metabolic diseases and pathogen infections." (PMID 39002673, 2024). "MCADD is an autosomal recessive inherited metabolic disorder caused by mutations to the ACADM gene on chromosome 1p31, ultimately impacting the function of MCAD." (PMID 36300606, 2023). "In severe cases, it can lead to encephalopathy, seizures, coma, and fatality, highlighting ACADM's substantial role in metabolic diseases." (PMID 39002673, 2024). "Metabolic diseases: Acyl-CoA Dehydrogenase Medium Chain (ACADM) is the gene that has been studied the most concerning metabolic problems in SIDS." (PMID 37465778, 2023). "This suggests that ACADM significantly affected metabolic disorders." (PMID 38664460, 2024).
infection (2 papers, 2010 to 2024). The state of being infected such as from the introduction of a foreign agent such as serum, vaccine, antigenic substance or organism. "We then infected Marc-145 cells with PEDV at different multiplicity of infections (MOIs) for 24 h to determine the expression of ACADM, and it displayed that the mRNA levels and protein levels of ACADM increased in a dose-dependent manner." (PMID 39002673, 2024). "qPCR and Western blot results showed that compared with the empty vector, the overexpression of ACADM significantly decreased the mRNA and protein levels of PEDV N, and the results of the median tissue culture infection dose also indicated that overexpression of ACADM decreased the titer of PEDV." (PMID 39002673, 2024).
kidney disease (1 paper, 2023). "From the datamining sources through network biology conducted by Cytoscape, it was found that ACADM, CROT, CRAT, and ACADS are the most prominent genes involved in the function of LC and in the pathology of kidney disease." (PMID 36836532, 2023).
ACADM also shares sentences with these, for which no sentence is quoted: carnitine deficiency (3 papers); galactosemia (3); clear cell renal cell carcinoma (2); genetic diseases (2); Hepatic steatosis (2); maple syrup urine disease (2); nonalcoholic fatty liver disease (2); steatosis (2); VLCAD) deficiency (2); ampullary adenocarcinoma (1); Argininosuccinic Acidemia (1); benign tumors (1); bladder urothelial carcinoma (1); cardiomyopathy (1); cholangiocarcinoma (1); chondropathies (1); citrullinemia type I (1); colon adenocarcinoma (1); congenital adrenal hyperplasia (1); Congenital erythropoietic porphyria (1); Crohn disease (1); cystic fibrosis (1); dyslipidaemia (1); esophageal carcinoma (1); glioblastoma (1); glioma (1); glutaric acidemia type 1 (1); glutaric aciduria (1); head and neck squamous cell carcinoma (1); heart failure (1).
A further 23 diseases each share a sentence with ACADM in 1 paper.